ENSG00000272104 (novel protein)
Gene: Protein-coding gene on chromosome 3 (50,350,892 to 50,367,923, forward strand). Ensembl gene ENSG00000272104.
Genetic constraint (gnomAD): Loss-of-function variants: 5 observed, 4.73 expected, observed/expected ratio (o/e) 1.06, 90% interval 0.54 to 1.84. That is too few expected variants to judge how well the gene tolerates losing a copy. Missense variants: 56 observed, 66.76 expected, observed/expected ratio (o/e) 0.84, 90% interval 0.68 to 1.05. Synonymous variants: 24 observed, 27.68 expected, observed/expected ratio (o/e) 0.87, 90% interval 0.63 to 1.22.